PPARA (peroxisome proliferator activated receptor alpha)
Diseases named in the same sentence as PPARA in open-access papers (continued):
Sharing a sentence is not in itself a finding about the gene and the disease.
heart failure (continued). "Recently, using a mouseheart failure model and hypoxic-reoxygenated H9c2 cells, ginsenoside Rb3 wasidentified as potentially having the best pharmacodynamic profile in terms ofexerting cardiac protection against indices of heart failure, exerting thesalutary effects primarily via PPARα activation." (PMID 39077021, 2023). "However, post hoc analyses of a large dyslipidaemia and diabetes trial have shown reduction in heart failure hospitalisation in patients treated with PPARα agonists, e.g. fenofibrate [49, 50•]." (PMID 36800045, 2023). "In the isolated PPARα deficient hearts, the decreased ATP synthesis is not sufficient for high workload challenge and resulted in progressive heart failure." (PMID 35479323, 2022). "This suggests that in the early stages of heart failure, the role of PPARα activation may be to restore FA oxidation, thereby, restoring energy production and cardiac function." (PMID 35055179, 2022). "However, PPARα activation in the early stage of TAC-induced mouse heart failure preserves myocardial function." (PMID 35185581, 2022). "However, suppression of the estrogen-related receptor transcriptional pathway by PPARα/SIRT1 as a physiological fasting response is involved in the progression of heart failure by inducing mitochondrial dysfunction." (PMID 33806509, 2021). "Previous reports showed that PPARα acts as a cofactor of Sirt1 and may repress mitochondrial gene transcription, leading to heart failure." (PMID 33073318, 2021). "In addition, activation of SirT3 accelerates glucose metabolism via upregulation of PPARα, and SirT3-induced metabolic reprogramming has been shown to sustain cardiomyocyte function in a mouse model of heart failure." (PMID 32721927, 2020). "Based on these reports, we rationalized that the activation of PPARα may attenuate the progression of heart failure." (PMID 29301869, 2018). "Recently, studies have demonstrated that cardiac dysfunction is deteriorated in PPARα knockout mice in response to chronic pressure overload, and suggested the pathology of heart failure is similar to that of diabetic cardiomyopathy in the heart of myosin heavy chain-PPAR-α transgenic mice." (PMID 28578382, 2017). "In line with our findings, chronic activation of PPARα upregulates the fatty acid metabolic pathway despite the accumulation of myocardial triglycerides without worsening left ventricular dysfunction in a rat infarct model of heart failure." (PMID 27413362, 2016). "Furthermore, protein levels of PPARα showed to be decreased in mice subjected to pressure overload, elucidating the metabolic substrate switch that characterizes end stage heart failure." (PMID 22723831, 2012). "Long chain fatty acids, including ω-3 PUFA are endogenous ligands for PPARα, which may prevent the decline in PPARα activation and mitochondrial function that is commonly observed in advanced heart failure." (PMID 20819225, 2010). "Although glitazars improved metabolic parameters, they induced cardiac failure, which is probably due to glucolipotoxicity through the combined increase of PPARγ-driven insulin sensitization and glucose uptake in the setting of higher PPARα-induced activation of fatty acid uptake and oxidation." (PMID 36768666, 2023). "Our findings that βOHB and FGF21 activate AMPK/PGC1α/PPARα signaling, and loss of FGF21 exaggerates serum βOHB elevation and promotes oxidative stress response in the heart contribute to the understanding of pathophysiological aspects of elevated serum βOHB and FGF21 in heart failure." (PMID 35513524, 2022). "In contrast, mild PPARα activation in mice showed a positive effect on myocardial energetic functions, especially during progressive and pressure-overloaded heart failure, revealing the virtue of PPARα-associated FAO modulation as a promising therapeutic strategy for heart failure." (PMID 34445672, 2021).
heart failure (continued). "A recent study in mice demonstrated that mildly increasing PPARα expression in the progressive phase of heart failure, when FAO is decreased, maintains myocardial function and energetics, suggesting that modulating substrate utilization may be a promising therapeutic strategy for heart failure." (PMID 29697773, 2018). "There are three PPAR subtypes—PPARα, PPARδ (also known as PPARβ), and PPARγ, which regulate gene expression in a variety of process, including lipid and glucose metabolism, atherosclerotic plaque formation, cellular differentiation, angiogenesis, inflammation, hypertension, and heart failure." (PMID 20613990, 2010). "After HFD loading, peroxisome proliferator-activated receptor-alpha/beta/gamma (PPAR-α/β/δ) transcriptional activation induces the fat-metabolizing enzyme CD36 and suppresses the onset of the heart failure in a pathological model." (PMID 36438601, 2022). "Additionally, analysis of cardiac substrate metabolism in PPARα knockout hearts indicated a substrate switch from FA to glucose and lactate but with an inability to respond to high energy demand, such as high workload, resulting in energetic and contractile failure mimicking end stage heart failure." (PMID 22723831, 2012). "While animal models of PPARα agonism have shown variable results, there have been no clinical trials specifically studying the effect of PPARα modulation on heart failure outcomes." (PMID 36800045, 2023). "First, different levels of PPARα expression are observed in individuals with HF characterized by FAO deficiency, suggesting that downregulated PPARα is not a common feature of heart failure." (PMID 35185581, 2022). "Nuclear hormone receptor PPARα, and fatty acid receptor CD36 which play a critical role in FA metabolism in the heart, especially when the heart is stressed or in heart failure, were decreased in left ventricle of chronic ritonavir-treated animals by ~40% and ~64%, respectively." (PMID 29691457, 2018). "Hence, understanding the mechanisms that regulate the activity of PPARα is crucial to determine the precise contribution of altered FAO at the genesis and progression to heart failure." (PMID 22723831, 2012). "Pterostilbene’s lipid-lowering effects may mimic those of peroxisome proliferator-activated receptor alpha (PPAR-α) agonists, known to reduce lipogenesis and lipid peroxidation, which are key drivers of multiorgan diseases such as liver disease and heart failure." (PMID 40611888, 2023). "Unlike the expression of PPARα, PPARγ is highly induced in heart failure." (PMID 37233656, 2023). "In this work, the PPARα levels were significantly enhanced under treatment with the Apelin, suggesting that the PPAR plays a critical role in the rescue of the cardiac function in D-IRI rats and may be an important mechanism of anti-heart failure in D-IRI rats." (PMID 33342766, 2020). "Thus, it does not appear that ω-3 PUFA preferentially activate PPARα under physiological conditions to confer cardioprotection in the setting of heart failure." (PMID 20819225, 2010).
lipid metabolism disorders (90 papers, 2013 to 2026). "The authors state that PFOA causes lipid metabolism disorders at least partly via the PPARα pathway, while the mechanism of PFOS-induced interference is not clear." (PMID 36814257, 2023). "DEHP causes lipid metabolism disorders by activating the PPARα or PPARγ signal transducer and farnesoid X receptor or liver X receptor signaling pathway, respectively." (PMID 35778735, 2022). "The downregulation of MFN2 is partly attributed to the decreased expression of the peroxisome proliferator-activated receptor alpha (PPARα) caused by the lipid metabolism disorder in DCM." (PMID 35450404, 2022). "Accordingly, modulation of PPARγ and PPARα is very important for tackling lipid metabolic disorder associated with obesity." (PMID 28248545, 2017). "Therefore, the AMPKα-SREBP-1c/PPARα pathway may be a key point in studying lipid metabolism disorders caused by transportation." (PMID 39518926, 2024). "In vitro experiments show that PHZ can upregulate PPARα expression in astrocytes with lipid metabolism disorders, as well as the downstream CPT1 and ACS gene and protein expression." (PMID 41300478, 2025). "This part focuses on the effects of FXR, LXR and PPARα on the glucose and lipid metabolism disorders in DM." (PMID 40650120, 2025). "In summary, these findings clearly highlight the value of PPARα and PPARγ as key therapeutic targets for regulating renal lipid metabolism disorders in DKD." (PMID 41170356, 2025). "In summary, CGE exhibited a significantly ameliorative effect on MASLD by upregulating PPARα to improve lipid metabolism disorder." (PMID 39334795, 2024). "To further verify that CGE ameliorated the lipid metabolism disorder by regulating PPARα, we knocked down the endogenous PPARα gene using PPARα siRNA." (PMID 39334795, 2024). "Numerous phenylpropanoic acid derivatives targeting three PPAR subtypes (PPARα, PPARγ and PPARδ) have been developed towards the treatment of serious diseases such as lipid-metabolism disorders." (PMID 35102897, 2022). "Chronic intermittent hypoxia (CIH) induced lipid metabolism disorder has been reported in several studies, most of which mainly focused on the regulation of two important genes, PPARA and ANGPTL4." (PMID 36153524, 2022). "Then, the results of ORO staining, TG assay and the levels of Pparα and Srebp1c showed that Rev-erbα shRNA improved lipid metabolism disorder and reduced lipid deposition." (PMID 34246287, 2021). "For instance, total flavonoids from Ligustrum lucidum were shown to have a beneficial regulatory effect on lipid metabolism disorder in rats in a high-fat model, possibly via regulation of the PPARα-LPL pathway and HMGCR expression." (PMID 31714944, 2019). "In the liver, both the NF-κB inhibitor and PPARα, down-regulated in the early stages and up-regulated in the late stages, indicating the final relief of hepatic inflammation and lipid metabolism disorder." (PMID 30246797, 2018). "Increases in the mRNA expression levels of Pparα and its target genes have also been identified as a mechanism for improving glucose and lipid metabolic disorders in high-fat diet-fed mice." (PMID 29681858, 2018). "Meanwhile, some related genes in PPARα signaling pathway were also down-regulated, which would further aggravate lipid metabolism disorder." (PMID 28389636, 2017). "Accumulating evidence has confirmed that promoting the expression of PPARα and its target genes is one of the mechanisms to improve glucose and lipid metabolism disorders in mice induced by high fat meals." (PMID 28885549, 2017). "Taken together, our study suggests that the activation of NHR-49/PPARα may be a promising strategy for the improvement of Aβ-induced lipid metabolic disorder and the inhibition of Aβ aggregation." (PMID 40338235, 2025).
lipid metabolism disorders (continued). "It is well established that PPARα serves as a master transcriptional regulator in lipid and cholesterol metabolism, both directly or indirectly, and has been proposed as a therapeutic target for lipid metabolic disorders." (PMID 40427382, 2025). "Specifically, LLPK intervenes in biological processes such as lipogenesis, fatty acid oxidation, and fatty acid transport in mice livers by regulating the expression of key downstream factors of PPARα (Scd1, Acox1, Acaa1b, Slc27a1, Acsl1, and Ehhadh), thus improving lipid metabolic disorders." (PMID 40431433, 2025). "In vivo, animal study results indicated that CGE could effectively reduce lipid metabolism disorder, inhibit oxidative stress, and upregulate PPARα protein in the liver of HFD-fed mice." (PMID 39334795, 2024). "HS induces lipid metabolism disorders in breast muscle and the PPARα gene may be the key gene in the mechanism of lipid metabolism." (PMID 38338073, 2024). "Combined with our bioinformatics analysis results, it can be inferred that the downregulated bile acid metabolism-related PPARα/CYP4A14 pathway in the liver may lead to the incidence of lipid metabolism disorder in LBW infants fed with HFD as adults." (PMID 36794015, 2023). "Therefore, the activation of the AMPK/PGC-1α/PPARα pathway to regulate skeletal muscle glucose and lipid metabolism disorders is an important measure for the treatment of prediabetes." (PMID 37391779, 2023). "Our findings of decreased ACC, Fasn and Srebp1c mRNA expression and increased PPARα mRNA expression in crocin-I treated mice suggest that crocin-I may play an important role in alleviating lipid metabolism disorders in the liver." (PMID 36034852, 2022). "It remains unclear whether miR-21 acts on PPARα and affects lipid metabolism disorders and mitochondrial dynamics, which are involved in the course of DKD." (PMID 35222033, 2022). "Based on these observations, we conclude that Atorvastatin inhibits tubular epithelial cell injury in T1DM with concomitant induction of lipid metabolism disorders by a mechanism involving inhibition of miR-21 expression and consequent upregulation of PPARα expression." (PMID 35222033, 2022). "In addition, fenofibrate is a peroxisome proliferator-activated receptor alpha activator (PPARα) involved in the regulation of lipid metabolism disorder, inflammation, oxidative stress, angiogenesis and apoptosis, which reduces the progression of DR." (PMID 36582230, 2022). "And more severe lipid metabolism disorders were occurred in Pparα-/- mice." (PMID 33052228, 2020). "A previous study had shown that AQP7 is up-regulated by fasting, low insulin and PPARα and altered expression may be related to lipid metabolism disorders." (PMID 31272371, 2019). "This relationship may be explained by the effects of PPARα agonists which are known to improve lipid metabolism disorder, and this capacity appears to be modulated by estrogens." (PMID 29484037, 2018). "Furthermore, we speculated and detected several key transcription factors as the potential regulatory effects in lipid metabolic disorders, PPARα, PPARγ, and SREBP1, and found their aberrant expression in the PM2.5 exposure group." (PMID 37780625, 2023). "In addition, long-term GTP ingestion markedly alleviates lipid metabolism disorders induced by a high-fat diet, which may be related to the up-regulation of hepatic PPARα expression." (PMID 28777810, 2017). "Our results have demonstrated that a 15-week GTP treatment improved the processing of atherosclerotic lesions, which may be involved in decreasing oxLDL in serum and up-regulating autophagy in the aorta, and alleviated lipid metabolism disorders via increasing hepatic PPARα expression." (PMID 28777810, 2017).
lipid metabolism disorders (continued). "These compounds reverse hepatic lipid metabolism disorders by activating the AMPK/SIRT1 and PPARα signaling pathways, inhibit lipogenesis by suppressing the key lipogenic factor SREBP-1c, and accelerate lipid catabolism by promoting fatty acid β-oxidation." (PMID 42283012, 2026). "The activation of the PI3K/Akt and PPARα/CPT-1 pathways in mice treated with HPM led to an obvious improvement in glucose and lipid metabolism disorders." (PMID 39201413, 2024). "TW suppresses the PPARα/PGC-1α pathway and impairs mitochondrial function, thus leading to lipid metabolism disorders and injury in mouse livers." (PMID 36541729, 2023). "Maternal nicotine exposure leads to lipid metabolism disorders and insulin resistance by activating PI3K/Akt signaling, inhibiting PPARα protein expression, and promoting the progression of MAFLD in adult offspring." (PMID 36359869, 2022). "In PPARαko mice, further evidence was found that the lack of PPARα exacerbated the inflammatory response phenotype as well as the lipid metabolism disorder in NASH-SD mice." (PMID 38633246, 2024). "PPARα, CRT1, ADRP, and ALBP were biomarkers of lipid metabolism disorder." (PMID 36248191, 2022). "Moreover, CACE can alleviate lipid metabolism disorder through inhibiting ER stress via PERK and ATF6 signaling pathways and activating PPARs with upregulating PPARα expression and downregulating PPARγ expression." (PMID 33688365, 2021). "Further mechanistic study showed that amelioration of lipid metabolism disorder by FSH may be mediated at least in part by suppressing PPARγ expression and upregulating PPARα expression, and inhibiting inflammation in adipose tissues." (PMID 28248545, 2017). "A single dose of the synthetic PPARα agonist WY14643 (WY, 80 mg/kg, i.p.)or chronic administration of fenofibrate, clinically available for lipid metabolism disorders, in the diet (0.2%) for 14 days significantly reduced or abolished behavioral and EEG expressions of nicotine-induced seizures." (PMID 23724059, 2013). "By stimulating the sirtuin 1 (SIRT1)/peroxisome proliferator-activated receptor alpha (PPARα)/Fibroblast growth factor 21 (FGF21) pathway, APS could alleviate lipid metabolism disorder, notably, by increasing hepatic glycolipid metabolism, reducing inflammation, and lipid droplet deposition." (PMID 35308224, 2022).